SVEP1 (sushi, von Willebrand factor type A, EGF and pentraxin domain containing 1)
Description:
Required for morphological development, cell alignment and migration of lymphatic endothelial cells during embryonic development, potentially via modulation of ANGPT2-TIE1 signaling and subsequent activation of FOXC2 transcription (By similarity). Required for embryonic lymphatic vascular development, via mediating the correct formation of the first lymphovenous contact site and tight association of the lymphatic endothelium with the venous endothelium (By similarity). Represses PRKCA-mediated L-type voltage-gated channel Ca(2+) influx and ROCK-mediated calcium sensitivity in vascular smooth muscle cells, via its interaction with integrins, thereby inhibiting vasocontraction. Promotes platelet activation, via its interaction with PEAR1 and subsequent activation of AKT/mTOR signaling. Plays a role in epidermal development and keratinocyte differentiation, independent of cell-cell adhesion. May play a role in initial cell attachment of stromal osteogenic cells (By similarity). May promote myoblast cell adhesion when in the presence of integrin ITGA9:ITGB1 (By similarity).
Synonyms: SEL-OB; C9orf13; CCP22; SELOB; bA427L11.3; POLYDOM; FLJ13529
Tractability: Antibody: UniProt places it where antibodies can reach, with high confidence; UniProt predicts a signal peptide or a membrane-spanning region; its Gene Ontology location is reachable by antibodies, with medium confidence. PROTAC: ubiquitination databases record sites on it.
Gene: Protein-coding gene on chromosome 9 (110,365,248 to 110,579,880, reverse strand). Ensembl gene ENSG00000165124.
Subcellular location: Secreted; Nucleus; Cytoplasm; Membrane
Gene Ontology:
Molecular function: integrin binding; protein binding; integrin binding involved in cell-matrix adhesion; calcium ion binding; chromatin binding
Biological process: negative regulation of vasoconstriction; positive regulation of platelet activation; epidermis development; lymph vessel morphogenesis; cell-matrix adhesion; circulatory system process; negative regulation of multicellular organismal process
Cellular component: cytoplasm; membrane; nucleus; extracellular region
Genetic constraint (gnomAD): Loss-of-function variants: 150 observed, 341.71 expected, observed/expected ratio (o/e) 0.44, 90% interval 0.38 to 0.5. The upper end of that interval is the gene's LOEUF score, 0.5, which puts it in group 2 of 6, group 1 being the genes least tolerant of losing a copy. Missense variants: 3,991 observed, 4,352 expected, observed/expected ratio (o/e) 0.92, 90% interval 0.89 to 0.94. Synonymous variants: 1,622 observed, 1,586.8 expected, observed/expected ratio (o/e) 1.02, 90% interval 0.98 to 1.07.
Homologues: Orthologues: chimpanzee SVEP1 (99% identical), macaque SVEP1 (97% identical), pig SVEP1 (87% identical), dog SVEP1 (87% identical), rabbit SVEP1 (87% identical), guinea pig SVEP1 (85% identical), rat Svep1 (82% identical), mouse Svep1 (82% identical), tropical clawed frog svep1 (63% identical), zebrafish svep1 (53% identical). Paralogues in human: CSMD3 (22% identical), CSMD2 (22% identical), CSMD1 (22% identical), CR1 (10% identical), CR2 (8% identical), CFH (6% identical), SELP (5% identical), SEZ6L (5% identical), SEZ6L2 (5% identical), SEZ6 (5% identical), PAPPA2 (5% identical), PAPPA (4% identical), and 27 more.
Diseases named in the same sentence as SVEP1 in open-access papers:
SVEP1 is named in the same sentence as 60 diseases in open-access papers, as found by Europe PMC text mining. Sharing a sentence is not in itself a finding about the gene and the disease. The quoted sentences say what the papers report.
atherosclerosis (11 papers, 2020 to 2025). A disease characterized by the build-up of fatty material and calcium deposition in the arterial wall resulting in partial or complete occlusion of the arterial lumen. "Despite confirmation that SVEP1 was causally related to the development of atherosclerosis, the cellular receptor responsible for mediating the effect of SVEP1 remained unclear." (PMID 38370227, 2024). "Recently, two studies investigated the effect of Svep1 deficiency in relation to the development of atherosclerosis in mice." (PMID 35802072, 2022). "Despite its strong association with CAD, the role of SVEP1 in atherosclerosis has yet to be determined." (PMID 33185739, 2020). "Notably, these studies, which utilised similar mouse models, detected contrary effects of Svep1 deficiency with one reporting a reduction in atherosclerosis and the other identifying an increase in plaque size." (PMID 35802072, 2022). "Similarly, a missense variant (encoding p.D2702G) in the SVEP1 gene was previously associated with an increased risk of coronary artery disease, while haploinsufficiency in mice has been linked to reduced burden of atherosclerosis." (PMID 38420755, 2024). "Svep1 increased proliferation and inflammation in murine vascular smooth muscle cells and promoted atherosclerosis." (PMID 40362725, 2025). "Using complimentary mouse models and human genetics, we confirmed that SVEP1 promoted the development of atherosclerosis and increased plaque complexity." (PMID 38370227, 2024). "Taken together, these results strongly suggest the presence of additional binding partners for SVEP1, at least one of which is responsible for mediating the effect of SVEP1 in the development of atherosclerosis." (PMID 38370227, 2024). "Plaques were larger in atherosclerosis-prone Svep1 haploinsufficient (ApoE−/−Svep1+/−) compared to Svep1 wild-type mice (ApoE−/−Svep1+/+) and ApoE−/−Svep1+/− mice displayed elevated plaque neutrophil, Ly6Chigh monocyte, and macrophage numbers." (PMID 33185739, 2020). "To better explore the impact of SVEP1 on atherosclerosis, we crossbred ApoE−/− mice with Svep1+/+ or Svep1+/− mice and hence generated atherosclerosis-prone mice with either normal (ApoE−/−Svep1+/+) or reduced (ApoE−/−Svep1+/−) wildtype Svep1 levels." (PMID 33185739, 2020). "In this project, we sought to investigate the functional involvement of SVEP1 in mice and patients with atherosclerosis." (PMID 33185739, 2020). "Our data provide a first insight into the role of SVEP1 in atherosclerosis." (PMID 33185739, 2020). "Given the well-reported connections between SVEP1 and atherosclerosis, it is plausible that regulation of lipoproteins, complement and coagulation cascades could provide novel mechanisms by which Svep1 mediates CAD, though further validation of this hypothesis is required." (PMID 39895831, 2025). "Together, these findings strongly suggest that integrin α9β1 is not responsible for mediating the SVEP1-induced promotion of atherosclerosis and support further studies aimed at characterizing other receptors whose interaction with SVEP1 may represent a therapeutically targetable interaction." (PMID 38370227, 2024). "Moreover, cluster 0 also expresses Svep1, which was recently shown to promote atherosclerosis in humans and mice, which is expressed by VSMCs within the atherosclerotic plaque cause proliferation and dysregulation of key differentiation pathways, including integrin and Notch signaling." (PMID 35163719, 2022). "Each gene was expressed in both cell types with SVEP1 and ITGA4 more highly expressed in VSMCs and ITGA9 expression higher in endothelial cells, in keeping with the previous atherosclerosis studies." (PMID 35802072, 2022). "While the molecular and cellular mechanisms involving ADAMTS-7 in atherosclerosis have not yet been elucidated, SVEP1 degradation may be involved." (PMID 33185739, 2020).
coronary artery disease (10 papers, 2020 to 2025). "A GWAS detected SVEP1 as a risk factor for coronary artery disease and knockout of Svep1 in mice is embryonic lethal, with multiple developmental defects." (PMID 35248088, 2022). "A missense variant of the sushi, von Willebrand factor type A, EGF and pentraxin domain containing SVEP1 has been associated with coronary artery disease." (PMID 36329547, 2022). "Gene-based approaches implicate the SVEP1 gene, a known contributor of coronary artery disease risk." (PMID 34131117, 2021). "Significant associations between coronary artery disease and low-frequency missense variants in SVEP1 have been discussed in previous studies." (PMID 32371982, 2020). "A missense variant of the sushi, von Willebrand factor type A, EGF and pentraxin domain containing protein 1 (SVEP1) is genome-wide significantly associated with coronary artery disease." (PMID 33185739, 2020). "Future work will need to address whether our newly identified connection between blood flow and Svep1 function is involved in the pathomechanisms underlying vessel loss, coronary artery disease or other aspects of vascular dysfunction in humans." (PMID 35312765, 2022). "Interestingly, however, Svep1 is evolutionarily highly conserved, and genotyping efforts by the Myocardial Infarction Genetics and CARDIoGRAM Exome Consortia identified missense variants in Svep1 associated with coronary artery disease and elevated blood pressure." (PMID 35312765, 2022). "Two highly conserved missense polymorphisms in SVEP1 exhibit significant genetic associations: rs111245230 (p.D2702G) associates with coronary artery disease (CAD), BP, and elevated SVEP1 plasma levels." (PMID 39895831, 2025). "SVEP1 is a substrate of the protease ADAMTS‐7, which also include genetic variants associated with CAD and BP, and contains the linear peptide sequences Arg‐Gly‐Asp (RGD) and Leu‐Asp‐Val (LDV) sequences." (PMID 35802072, 2022). "Despite strong causal associations with cardiovascular and metabolic disorders including coronary artery disease, hypertension, and type 2 diabetes, as well as a range of other diseases, the exact function of the protein SVEP1 remains largely unknown." (PMID 39895831, 2025).
hepatocellular carcinoma (6 papers, 2020 to 2025). A malignant tumor that arises from hepatocytes. "In our previous studies, we found and reported that SVEP1, as a promising novel diagnostic and prognostic biomarker, plays various regulatory roles in the malignant progression of hepatocellular carcinoma." (PMID 36699464, 2022). "SVEP1, a gene of significant interest in our previous studies on hepatocellular carcinoma (HCC), was identified among the downregulated mRNAs in the high recurrence group." (PMID 41315239, 2025). "Previous studies demonstrate that decreased SVEP1 expression in hepatocellular carcinoma (HCC) induces malignant phenotype transformation, promoting multiple metastases and invasion into osteophagy in vivo." (PMID 41315239, 2025). "For example, miR-1269b regulates the expression of SVEP1, affecting the proliferation and metastasis of hepatocellular carcinoma." (PMID 41229443, 2025). "Our previous studies demonstrated that the low-SVEP1 expression has an increased likelihood of having increased tumor sizes in patients with hepatocellular carcinoma." (PMID 36699464, 2022). "SVEP1 is involved in the regulation of intercellular adhesion, and its aberrant expression can induce hepatocellular carcinoma proliferation and metastasis." (PMID 34308747, 2021).
Hypertension (6 papers, 2016 to 2025). The presence of chronic increased pressure in the systemic arterial system. "Mouse models have been instrumental in studying cardiometabolic diseases including CAD and hypertension, with Svep1 deficient mouse models yielding varying outcomes." (PMID 39895831, 2025). "Given the association of SVEP1 with hypertension, we also tested the cardiovascular manifestations of Svep1 deletion using the same mouse cohort." (PMID 36792666, 2023). "Similar associations were observed between a protective BD allele (T) at SNP rs7042161 in the SVEP1 gene and ‘essential hypertension' (OR=0.90; P=3.5 × 10−3)." (PMID 27529678, 2016). "Moreover, we present additional evidence supporting these associations, particularly the association of the SVEP1 SNP with hypertension." (PMID 27529678, 2016). "The SVEP1 SNP with suggestive evidence of association with essential hypertension in our study is included in the online PheWAS catalog, with the results supporting our findings (P=0.0075 for association with hypertension; P=0.0086 for association with essential hypertension)." (PMID 27529678, 2016). "The top association findings suggested that the BD risk alleles at SNP rs4765913 in CACNA1C gene and rs7042161 in SVEP1 may be associated with increased risk of ‘cardiac dysrhythmias' (odds ratio (OR)=1.1, P=3.4 × 10−3) and ‘essential hypertension' (OR=1.1, P=3.5 × 10−3), respectively." (PMID 27529678, 2016). "Mendelian randomization (MR) analyses indicate causal associations between higher plasma SVEP1 and type 2 diabetes (T2D), platelet traits, CAD, hypertension and dementia." (PMID 39895831, 2025). "The association between SVEP1 (Sushi, Von Willebrand Factor Type A, EGF And Pentraxin Domain Containing 1) gene variants and essential hypertension also warrants attention." (PMID 27529678, 2016). "Despite strong causal associations with cardiovascular and metabolic disorders including CAD, hypertension, and T2D, as well as a range of other diseases, the exact function of the protein SVEP1 remains largely unknown." (PMID 39895831, 2025). "We observed MR evidence for associations between genetically regulated levels of 7 proteins and HF risk factors including: SPON1, CCL15, and ITIH3 with hypertension; SVEP1 and SPON1 with atrial fibrillation; FSTL3 and NRP1 with diabetes; and APOF, CCL15, ITIH3, and NRP1 with CHD." (PMID 38225249, 2024). "Comparison of these groups of patients provided independent marginal evidence for association of the SVEP1 SNP rs7042161 with hypertension (OR=0.80, P=0.054 without sex adjustment; OR=0.82, P=0.082 after correction for sex)." (PMID 27529678, 2016). "Still, an increased expression of SVEP1, NRP1, RNASE1, QSOX1, and GKN1, along with decreased expression of XYLT2, CFH, LEP, and CETP serum levels were found in patients with hypertension." (PMID 37792298, 2023).
breast carcinoma (5 papers, 2013 to 2025). "The cell adhesion molecule SVEP1 has been recently involved in the interactive network that affects breast cancer cells homing to bone niches." (PMID 24285959, 2013). "Then, further studies confirmed that 17βE2 and TNFα could promote the expression of SVEP1 by activating the promoter of SVEP1 in breast cancer cells." (PMID 36699464, 2022). "Recently, Glait-Santar and colleagues have investigated the alternative splicing of SVEP1 transcripts in a co-culture model of pre-osteoblastic MDA-15 and mammary adenocarcinoma DA3 cells, which mimic the molecular interactions in the bone niche after invasion of breast carcinoma cells." (PMID 24285959, 2013).
dementia (5 papers, 2022 to 2025). Loss of intellectual abilities interfering with an individual's social and occupational functions. "The increased dementia risk in individuals with high levels of plasma SVEP1, HE4, CDCP1, SIGLEC‐7, MARCKSL1, CRDL1, or RNAS6 is a novel finding." (PMID 34338426, 2022). "Svep1 also has positive, causal associations with dementia, with lipids playing a complex role in dementia disease pathology, presenting a potential role for the involvement of SVEP1." (PMID 39895831, 2025).
glaucoma (5 papers, 2020 to 2025). Increased pressure in the eyeball due to obstruction of the outflow of aqueous humor. "All five alleles were rare and had CADD scores over 25, further supporting an association between SVEP1 gene variants and glaucoma." (PMID 33027505, 2020). "Moreover, common variants in ANGPT1and SVEP1 have been identified as risk alleles for primary open angle glaucoma (POAG) in GWAS studies." (PMID 34663817, 2021). "Since compound heterozygous mutations for SVEP1 and TIE2 have recently been reported in human glaucoma patients, our data have clinical relevance in demonstrating a role for SVEP1 in TIE signalling in an in vivo setting." (PMID 37097004, 2023).
atrial fibrillation (3 papers, 2024 to 2025). A disorder characterized by an electrocardiographic finding of a supraventricular arrhythmia characterized by the replacement of consistent P waves by rapid oscillations or fibrillatory waves that vary in size, shape and timing and are accompanied by an irregular ventricular response. "For the observed associations for NPPB, ITIH3, and IGFBP7 with multiple outcomes and for the association of SVEP1 with atrial fibrillation, our findings were negative for colocalization, suggesting two different causal variants for protein level and outcome." (PMID 38225249, 2024).
myocardial infarction (3 papers, 2022 to 2023). Gross necrosis of the myocardium, as a result of interruption of the blood supply to the area, as in coronary thrombosis. "Notably, human genetic studies have identified associations between variants in both SVEP1 and integrin α9β1 and BP." (PMID 35802072, 2022).
urothelial bladder cancer (3 papers, 2024 to 2025). "YY1 promotes the secretion of exosomes to promote prostate cancer progression, and YY1 upregulates polycom, also named pentraxin domain containing 1 (SVEP1), in cancer-associated fibroblasts (CAFs), which secrete miR-146a-5p and increase urothelial bladder cancer resistance." (PMID 40867514, 2025). "On the other hand, an upregulation of SVEP1 in CAFs compared to normal fibroblasts, and its involvement in chemoresistance to gemcitabine and cisplatin, has been recently described in urothelial bladder cancer." (PMID 39202425, 2024). "CAF-derived miR-146a-5p can promote stemness and enhance chemoresistance in urothelial bladder cancer via regulating YY1/SVEP1 and ARID1A/PRKAA2 signal pathways." (PMID 38737906, 2024).
diabetes (2 papers, 2023 to 2024). "We observed evidence of colocalization for observed MR associations for SPON1, CCL15, and FSTL3 with multiple outcomes; for SVEP1 with HF; and for NRP1 with diabetes and CHD." (PMID 38225249, 2024).
liver cancer (2 papers, 2019 to 2022). An epithelial or non-epithelial malignant neoplasm that arises from the liver. "miR-1269b can activate the PI3K/Akt signaling pathway by inhibiting SVEP1 in liver cancer cells, thereby promoting tumor recurrence and metastasis." (PMID 35252180, 2022). "In liver cancer cells, down-regulation of SVEP1 expression can significantly enhance the Akt phosphorylation at Thr308, thereby promoting the proliferation and metastasis of liver cancer cells." (PMID 35252180, 2022).
open-angle glaucoma (2 papers, 2022 to 2025). Chronic outflow obstruction of the eye's drainage canals that can lead to increased internal eye pressure and optic nerve damage. "A SVEP1 missense allele has also been shown in humans to modify the severity of TEK disease–causing mutations, and a common SVEP1 missense allele is also associated with adult-onset primary open-angle glaucoma (POAG)." (PMID 36453543, 2022).
Sepsis (2 papers, 2019 to 2022). Sepsis is defined as life-threatening organ dysfunction caused by a dysregulated host response to infection. "The rs7038903 common variant in SVEP1 gene showed significant association with sepsis severity independent of other variants in ordinal logistic and linear regression model (p = 0.001 and p = 0.002, respectively)." (PMID 31097890, 2019). "Our study shows a promising polymorphism in SVEP1 gene (rs7038903) which isassociated with sepsis shock and 28 days mortality, independent of age, gender, and method of diagnosis and SOFA score." (PMID 31097890, 2019).
type 2 diabetes (2 papers, 2016 to 2025). "Six out of twenty selected genes with largest expression difference (CYP1B1, GPT), genes linked to PCOS (RAB5B) or type 2 diabetes (PPARG, SVEP1), and methylation (DMAP1) were replicated in a separate case-control study." (PMID 26975253, 2016).
agranulocytosis (1 paper, 2020). "If these signals indeed represent true causal associations, a potential underlying mechanism involving the intergenic locus on chromosome 9, or the SVEP1 locus in agranulocytosis may not apply to metamizole-induced neutropenia." (PMID 33138277, 2020).